FGF2 (fibroblast growth factor 2)
Diseases named in the same sentence as FGF2 in open-access papers (continued):
Sharing a sentence is not in itself a finding about the gene and the disease.
osteoporosis (18 papers, 2011 to 2025). A condition of reduced bone mass, with decreased cortical thickness and a decrease in the number and size of the trabeculae of cancellous bone (but normal chemical composition), resulting in increased fracture incidence. "They not only found an association of this variant with low BMD, but also identified aberrant expression of the FGF2 gene in women with osteoporosis, with the rs6854081 locus being associated with altered osteoclast differentiation." (PMID 39411371, 2024). "The current study investigated the potential relevance of FGF-2 gene polymorphism in osteoporosis among a Zhuang ethnic Chinese cohort of 623, including 237 normal bone mass controls, 227 osteopenia, and 159 osteoporosis of different ages." (PMID 28653999, 2017). "In this study, to determine the association of FGF-2 SNPs with osteoporosis, LD analyses were performed by pairs of the five polymorphic loci of FGF-2, and D’ and r2 were comprehensively analyzed." (PMID 28653999, 2017). "The increase of expression in FGF-2 in the bone has been suggested to promote the occurrence and development of osteoporosis and is associated with pathogenesis of osteoporosis." (PMID 28653999, 2017). "To further investigate the relevance of the FGF2 gene to osteoporosis and to provide complementary evidence supporting the associations detected earlier, we performed differential expression analyses for the FGF2 gene in three distinct gene expression studies." (PMID 20641033, 2011). "Interestingly, rs8109113 in the FGF22 gene was associated with both hypertension and height, and 17 SNPs in FGF10, FGF18, and FGF2 were associated with both osteoporosis and height." (PMID 35980984, 2022). "Therefore, the relationship between FGF-2 polymorphism and osteoporosis cannot be judged through LD analysis results." (PMID 28653999, 2017). "In addition, differences in the FGF-2 gene polymorphism in five SNP loci between osteoporosis patients and individuals with normal bone mass were assessed, and the linkage disequilibrium (LD) of FGF-2 in the five SNP loci was evaluated." (PMID 28653999, 2017). "Moreover, the loss of FGF-2 was accountable for the reduced number of osteoclasts, altered proliferation and differentiation of osteoblasts, and development of osteoarthritis (OA) and osteoporosis compared to wt littermates." (PMID 33396566, 2020). "Out of five FGF-2 SNP loci, the TA genotype of rs308442 in the osteoporosis group (40.2%) was higher than in the control group (29.5%) (p < 0.05)." (PMID 28653999, 2017). "The distribution frequency of the TA genotype in the rs308442 of the FGF-2 gene in the normal group (50 cases) was significantly lower than that in the Osteopenia group (84 cases) or that in Osteoporosis group (91 cases) (p < 0.05)." (PMID 28653999, 2017). "Fibroblast growth factor-2 (FGF2) has been demonstrated to be a promising osteogenic factor for treating osteoporosis." (PMID 22629419, 2012). "Although its effect may be limited, these results suggest that FGF-2 promotes periodontal regeneration even under conditions of impaired bone metabolism, such as osteoporosis." (PMID 40722440, 2025). "Given the high prevalence of osteoporosis in humans, future studies using appropriate osteoporosis models with longer observation periods may provide deeper insights into the effects of FGF-2 on periodontal regeneration under compromised bone conditions." (PMID 40722440, 2025). "This study aimed to investigate the effects of local FGF-2 application on two fronts: the healing of surgically created periodontal defects in an osteoporosis rat model, and the behavior of bone marrow mesenchymal stromal cells (BMSCs) obtained from osteoporotic rats." (PMID 40722440, 2025). "The in vitro and in vivo findings from the present study demonstrated the disruption of bone repair in osteoporosis while also revealing that FGF-2 still promotes novel bone formation, albeit with attenuated yet substantial efficacy compared to non-osteoporotic states." (PMID 40722440, 2025).
osteoporosis (continued). "Similarly, the FGF2, FGF4, FGF10, FGF18, and FGF22 genes, which showed interactions with the FGFRL1 gene, were associated with height, hypertension, and osteoporosis." (PMID 35980984, 2022). "Thus, based on these previous studies and our current data, FGF-2 signal pathway participates in the occurrence and development of osteoporosis." (PMID 28653999, 2017). "Thus, the rs308442 locus of FGF-2 gene is closely correlated to osteoporosis in this Zhuang ethnic Chinese cohort, and the TA may be the risk genotype of osteoporosis." (PMID 28653999, 2017). "Intraosseous administration of exogenous FGF2, a muscle-derived osteogenic growth factor, has demonstrated its efficacy in enhancing bone formation in ovariectomized (OVX) rats with osteoporosis." (PMID 39066929, 2024). "The FGF10, FGF18, FGF2, FGF4, and FGF22 genes, which interact with FGFRL1, were correlated with height, hypertension, and osteoporosis." (PMID 35980984, 2022). "Similar to FGF-2 isoform-specific ko mice, these strains are also viable and fertile, whereby FGF-2HMWtg mice displayed osteomalacia and dwarfism together with age-related osteoporosis." (PMID 33396566, 2020). "While evidence above confirmed that FGF-2 plays an important role in bone formation and bone mass determination, the relationships between FGF-2 genetic diversity with bone mineral density (BMD) and with risk of osteoporosis have not yet been revealed." (PMID 28653999, 2017). "FGF2 plays a vital role in varieties of biological processes, such as morphogenesis, embryonic development, tissue repair, tumor growth and invasion, and functions in varieties of diseases, e.g., chronic kidney disease (CKD), cancers, osteoporosis, and traumatic brain injury." (PMID 37919618, 2024). "Therefore, FGF2 has potential therapeutic applications in bone-related diseases such as severe osteoporosis that are not responsive to present therapy and bone defects." (PMID 39066929, 2024). "Therefore, they believed that exogenous FGF-2 can maintain osteogenesis and inhibit muscular atrophy in the presence of GC, suggesting that FGF-2 may be a potential target for the treatment of osteoporosis." (PMID 35574015, 2022). "Next, the efficacy of FGF2/HGF priming on the osteogenic potential of ADSCs from donors with chronic diseases will be widely evaluated, and its effect on bone defects will be confirmed using a non-clinical osteoporosis model." (PMID 35805126, 2022).
thyroid cancer (18 papers, 2006 to 2025). "LncRNAs also regulate the induction of angiogenesis, with MALAT1 in particular enhancing neovascularization by promoting FGF2 secretion from tumor-associated macrophages in thyroid cancer, which supported tumor growth and metastatic potential." (PMID 41154428, 2025). "MALAT1 promotes the formation of blood vessels in thyroid cancer by regulating the secretion of the FGF2 protein in tumor-associated macrophages (TAMs), thereby promoting biological behaviors such as proliferation and metastasis in thyroid cancer cells." (PMID 32596158, 2020). "Afterwards, FGF2 was proven to be associated with lymph node invasion and distant metastasis in differentiated thyroid cancers." (PMID 28740507, 2017). "Furthermore, MALAT1 could promote angiogenesis of thyroid cancer by regulating tumor-associated macrophage FGF2 protein secretion." (PMID 30988072, 2019). "LncRNA-MALAT1 (metastasis-associated lung adenocarcinoma transcript 1) is highly expressed in TAMs and promotes the secretion of FGF2, thus promoting the proliferation, migration, and invasion of thyroid cancer cells." (PMID 38933287, 2023). "LncRNA-MALAT1 knockdown in TAMs inhibits the propagation of thyroid cancer cells, and FGF2 overexpression rescues the inhibitory effects of MALAT1, indicating that lncRNA-MALAT1 exerts its role in an FGF2-dependent manner." (PMID 38933287, 2023). "MALAT-1-dependent FGF2 secretion by TAMs inhibited the secretion of pro-inflammatory cytokines, promoted proliferation, migration, and invasion of thyroid cancer cells and increased angiogenesis." (PMID 34209679, 2021). "Another highly-expressed lncRNA in thyroid cancer, MALAT1, can activate angiogenesis via increasing fibroblast growth factor 2 (FGF2) expression in tumor-associated macrophages." (PMID 33158279, 2020). "Based on these observations, we can state that PROX1 and FGF2 remain in close relation also in thyroid cancer and regulate two signaling pathways, which cross each other." (PMID 31717665, 2019). "In addition, FGF2 can promote angiogenesis in thyroid cancer through the regulation of the lncRNA MALAT1." (PMID 38393692, 2024). "While the blood concentration of VEGF was similar between control healthy subjects and patients with cancer, blood concentrations of FGF-2 were significantly higher in patients with thyroid cancer compared with controls (29.52 ± 4.99 vs. 6.05 ± 1.43 pg/mL; p < 0.001)." (PMID 36139603, 2022). "It suggests that FGF2 plays an important role in thyroid cancer progression." (PMID 28740507, 2017). "However, some studies have reported that FGF2 was up-regulated in thyroid cancer and SLC2A5 was up-regulated in lung adenocarcinoma, which was inconsistent with our results may be due to the different cancer type and genetic background." (PMID 37980162, 2023). "High levels of expression of MALAT-1 and FGF2 were detected in M2-polarized THP-1 cells and TAMs (THP-1 cells stimulated by CM from thyroid cancer FTC133 cells) in vitro." (PMID 34209679, 2021). "In thyroid cancer, lncRNA MALAT1-mediated fibroblast growth factor-2 (FGF2) secretion from TAMs depresses release of inflammatory cytokines, induces vasculature formation and accelerates proliferation, invasion and migration of tumor cells." (PMID 33148302, 2020). "FTC is a relatively rare form of thyroid cancer, so we analyzed results of PROX1 and FGF2 expression in the PTC subtype available through the GEPIA database (Gene Expression Profiling Interactive Analysis)." (PMID 31717665, 2019). "Interestingly, the treatment of CGTH-W-1 with FGF2 resulted in the higher expression of PROX1, which indicates mutual regulation of PROX1 and FGF2 signaling generating a regulatory loop in thyroid cancer cells." (PMID 31717665, 2019). "However, in all tested thyroid cancer cell lines and tissues of different origins, we observed the inverse PROX1:FGF2 relation." (PMID 31717665, 2019).
thyroid cancer (continued). "We can assume that PROX1 functions as a transcription repressor for the FGF2 gene, but by itself is upregulated by FGF2 stimulation, thereby contributing to the negative feedback loop of FGF2 signaling in thyroid cancer cells." (PMID 31717665, 2019). "Then, using a number of cell lines from various thyroid cancer subtypes, we checked whether the negative correlation of PROX1 and FGF2 expression is a characteristic feature of FTCs or whether it occurs also in other thyroid cancers, such as PTCs and anaplastic cancer." (PMID 31717665, 2019).
Alzheimer disease (17 papers, 2013 to 2025). A progressive, neurodegenerative disease characterized by loss of function and death of nerve cells in several areas of the brain leading to loss of cognitive function such as memory and language. "Studies indicate that the Fgf2 gene is closely associated with Alzheimer’s disease and other neurological and cognitive disorders." (PMID 38493090, 2024). "Subsequent research endeavors have shed light on the role of Fgf2 in influencing tau protein phosphorylation, a process intimately tied to various neurodegenerative conditions, including Alzheimer’s disease." (PMID 38493090, 2024). "In the context of gene therapy for treating Alzheimer’s disease, the therapeutic potential of Fgf2 by stimulating NSCs in neurodegenerative disorders has already been demonstrated." (PMID 37763262, 2023). "The fibroblast growth factor (Fgf2) gene is an SHH-responding proneural gene able to restore hippocampal functions in a model of Alzheimer’s disease, partly as a result of enhanced neurogenesis." (PMID 34830484, 2021). "Here, we show that total sulfated GAGs from hippocampus of Alzheimer’s disease have altered capacities to bind and potentiate the activities of growth factors including FGF-2, VEGF, and BDNF while their capacity to bind to tau is remarkable increased." (PMID 30608949, 2019). "Several studies reported an induction and binding of FGF2 to the plaques and neurofibrillary tangles in brains affected by Alzheimer’s disease, and in cerebrospinal fluid (CSF) obtained from Alzheimer’s disease patients." (PMID 28974056, 2017). "In mouse model, the alleviation of Alzheimer’s disease was experimentally achieved by hippocampal delivery of the oncogenic fibroblast growth factor FGF2." (PMID 24196233, 2013). "Although FGF1 may be involved in the pathophysiology of Alzheimer’s disease similar to FGF2, more studies need to be commenced to deduce the exact molecular signaling pathways." (PMID 28974056, 2017). "Moreover, FGF-2 gene delivery restores hippocampal functions in an Alzheimer’s disease mouse model." (PMID 24735639, 2014).
Kaposi's sarcoma (17 papers, 2006 to 2026). A malignant neoplasm characterized by a vascular proliferation which usually contains blunt endothelial cells. "This process is triggered by factors such as transforming growth factor beta (TGF-β) and fibroblast growth factor 2 (FGF2) deficiency, chronic inflammation, and viral infection (e.g., KSHV in Kaposi’s sarcoma)." (PMID 41562845, 2026). "Accordingly, FGF2 has been shown to play an important role in the pathology of tumors of endothelial cell origin, such as hemangiomas and Kaposi's sarcoma." (PMID 25609197, 2015). "Accordingly, in phase I and II clinical trials it leads to stabilization of Kaposi’s sarcoma, a lesion in which Tat and FGF2 act synergistically." (PMID 25867824, 2015). "Moreover, CDV reduces the growth of primary murine B16 melanoma tumor grafts and of Kaposi's sarcoma-like tumors induced by murine FGF2-overexpressing FGF2-T-MAE cells." (PMID 25609197, 2015). "Moreover, Tat and FGF-2 synergize to induce an aggressive and highly angiogenic phenotype of AIDS-Kaposi’s sarcoma." (PMID 25429350, 2014).
small cell lung carcinoma (17 papers, 2011 to 2023). Small cell lung cancer (SCLC) is a highly aggressive malignant neoplasm, accounting for 10-15% of lung cancer cases, characterized byrapid growth, and early metastasis. "FGF2 has also been implicated in the antiapoptotic traits and chemoresistance of small cell lung cancer." (PMID 35879299, 2022). "High levels of serum FGF2 have been observed in individuals with small cell lung cancer and are associated with a poor prognosis." (PMID 26094024, 2015). "S6K2 has also been suggested as an effector under fibroblast growth factor-2 (FGF2) stimulation, inducing the survival of small cell lung cancer cells and chemoresistance via the formation of a complex with B-Raf and PKCε." (PMID 35879299, 2022). "FGF2 has been shown to protect small-cell lung cancer cells from apoptosis by enhancing the expression of the anti-apoptotic proteins XIAP and Bcl-XL." (PMID 34831463, 2021). "For instance, in small cell lung cancer, FGF2 increased the expression of anti-apoptotic proteins and triggered chemoresistance." (PMID 31877723, 2019). "The greatly improved cytotoxic action of FGF2 dual warhead conjugate is perfectly illustrated by the example of small cell lung cancer line NCI-H446." (PMID 30029518, 2018). "S6K2 was also shown to promote fibroblast growth factor-2 (FGF2)-mediated survival of small cell lung cancer (SCLC) cells." (PMID 28301598, 2017). "The relevance of our findings to cancer is further supported by the fact that similar results to those in HEK293 cells were obtained in small-cell lung cancer cells where FGF-2 drives cytotoxic drug-resistance." (PMID 25324306, 2014). "In small-cell lung cancer cells, Downward and colleagues have demonstrated that FGF2 inhibits etoposide-mediated caspase 3 activation downstream cytochrome c." (PMID 21637382, 2011). "In this way, FGF2 induces chemoresistance in small-cell lung cancer cells." (PMID 34831463, 2021). "Original data indicated reduced growth of small cell lung carcinoma H-69 cells expressing a dominant negative PI3K-C2β upon stimulation with stem cell factor but not with insulin or fibroblast growth factor-2." (PMID 31752944, 2019). "Decreasing the expression of FGF2/EGR-1 pathway may also become an effective method to reduce the angiogenesis and vascular motion in small cell lung cancer." (PMID 26901069, 2016).
Arthritis (16 papers, 2005 to 2023). Inflammation of a joint. "Here we found that FGF2 also synergized with IL-17 to induce ERK activation to promote autoimmune inflammation during the pathogenesis of arthritis." (PMID 28765647, 2017). "In the present study, we utilized the chondrocytic ATDC5 cell line to examine the role of IL-1β, the major inflammatory cytokine during arthritis, in the expression of the pro-angiogenesis factor FGF-2." (PMID 26811540, 2016). "IHC (immunohistochemistry) staining from a CIA (collagen-induced arthritis) mouse model also demonstrates that arthritis increased the expression of IL-1β and FGF-2, as well as EPC homing in articular cartilage." (PMID 26811540, 2016). "In the present study, IL-1β (10 ng/ml) promoted 80 pg/ml FGF-2 expression in chondrocytes; this result is consistent with severe arthritis patients in the clinic." (PMID 26811540, 2016). "During arthritis, IL-1β-induced catabolic processes promote matrix degradation and result in the formation of microcracks in the cartilage, which leads to FGF-2 release." (PMID 26811540, 2016). "In view of the strong anti‐inflammatory role of TSG‐6 in other arthritis models and its strong FGF2‐dependent gene regulation, in this paper we explore the hypothesis that the chondroprotective properties of FGF2 may in part be mediated through TSG‐6." (PMID 33029956, 2020). "FGF2 blocking antibody significantly reduces adjuvant-induced arthritis (AIA) pathogenesis in rat29, suggesting FGF2 may be important for joint inflammation." (PMID 28765647, 2017). "In the present study, we found that IL-1β, a key inflammatory cytokine during arthritis, induces the expression of the angiogenic factor FGF-2 in chondrocytes, and subsequently promotes EPC migration and tube formation through the activation of the IL-1RI/ROS/AMPK/p38/NF-κB signalling pathway." (PMID 26811540, 2016). "Therefore, it is proposed that high levels of FGF-2 may be involved in promoting p38 MAPK-mediated arthritis and inflammatory responses in patients with AOSD." (PMID 32381117, 2020). "Hence, it cannot be concluded whether the observed suppression in arthritis scores was primarily due to the aptamer-driven suppression in inflammation or to curing in bone disorders since FGF2 has an angiogenesis activity." (PMID 27506449, 2016). "The most common pathway employed by FGF-2 is the p38 mitogen-activated protein kinase (MAPK) pathway, which has been suggested to exacerbate arthritis and bone destruction in RA." (PMID 32381117, 2020). "Their results suggested that FGF-2 modulated disease progression, but did not affect initiation of the arthritis." (PMID 30377863, 2018). "First, we did not have clinical arthritis samples to evaluate the expression of IL-1β and FGF-2, as well as EPC recruitment in articular cartilage." (PMID 26811540, 2016).